GABRG2 (gamma-aminobutyric acid type A receptor subunit gamma2)
Diseases named in the same sentence as GABRG2 in open-access papers (continued):
Sharing a sentence is not in itself a finding about the gene and the disease.
glioma (6 papers, 2009 to 2025). A benign or malignant brain and spinal cord tumor that arises from glial cells (astrocytes, oligodendrocytes, ependymal cells). "We previously reported that high levels of GABRA2, GABRA3, GABRB3, GABRG1, and GABRG2 indicated better prognosis in glioma, and GABRB3 was particularly associated with longer OS in patients with lower-grade gliomas." (PMID 39595908, 2024). "In patients with lower grade gliomas, GABRA3, GABRB3, GABRG1, and GABRG2, were associated with longer OS." (PMID 38539663, 2024). "Immunocytochemistry for neuronal (neurofilament) and glioma (nestin) markers, together with a presynaptic marker (synapsin 1) and GABRG2–GFP revealed colocalization of neuronal presynaptic puncta with glioma postsynaptic GABRG2–GFP puncta by confocal microscopy." (PMID 39972132, 2025).
schizophrenia (6 papers, 2011 to 2025). A major psychotic disorder characterized by abnormalities in the perception or expression of reality. "A secondary network analysis of significantly altered focus and reference proteins associated the IL-1 receptor with SERPINA3, GABRG2, GAD2, and IRAK1 with schizophrenia and related disorders (early-onset schizophrenia, schizoaffective disorder, and psychosis)." (PMID 33976392, 2021).
tonic-clonic seizures (6 papers, 2016 to 2023). "The most common phenotypes associated with GABRG2 mutations are febrile seizures, generalized tonic-clonic seizures with febrile plus (GEFS+), and DS, with febrile seizures being the core phenotype." (PMID 36077081, 2022). "Mice expressing the GABRG2 (Q390X) mutation showed a severe epileptic phenotype, which included spontaneous generalized tonic-clonic seizures in a seizure-resistant C57BL/6J mouse background." (PMID 36077081, 2022). "Heterozygous mice with a targeted deletion of Gabrg2 (Gabrg2+/-) have absence seizures but no spontaneous generalised tonic-clonic seizures (GTCS)." (PMID 34050134, 2021).
Epileptic encephalopathy (5 papers, 2016 to 2024). A condition in which epileptiform abnormalities are believed to contribute to the progressive disturbance in cerebral function. "Several de novo GABRG2 pathogenic variants, including P282S, F343L, and I107T, have been reported to induce epileptic encephalopathy in patients." (PMID 38357846, 2024). "GABRG2(P282S) missense mutation was first detected in a patient with epileptic encephalopathy, who had secondary generalized seizure onset at 1 year old and followed by atypical absences." (PMID 38357846, 2024). "The phenotypic spectrum observed for GABRG2 variants, ranging from febrile seizures to epileptic encephalopathy, is similar to those of the other GABAA receptor genes GABRA1, GABRB2, and GABRB3." (PMID 35359574, 2022). "Zou reported that seizures were effectively controlled in two patients with GABRG2 variant (A106T)- related epileptic encephalopathies after treatment with oxcarbazepine." (PMID 35359574, 2022). "Currently, patients with the GABAA receptor-related GABRA1 and GABRG2 genes, ranging from genetic generalized epilepsy to epileptic encephalopathy, have been found to be photosensitive." (PMID 36034301, 2022).
cocaine addicts (3 papers, 2012 to 2020). "Enoch and colleagues (2012) found that the expression of GABRG2 was down‐regulated in both the brains of alcoholics and cocaine addicts." (PMID 31840818, 2020). "In contrast, GABRG2 was significantly down-regulated in alcoholics and cocaine addicts relative to controls and likewise GPHN was down-regulated in cocaine addicts." (PMID 22253714, 2012). "Considering only the major loadings on this factor, none of the genes, with the exception of GABRG2, showed altered hippocampal expression in alcoholics and cocaine addicts." (PMID 23717525, 2013).
developmental delay (3 papers, 2020 to 2022). "We observed developmental delay in 42.8% (15/35) of patients with GABRG2 variants, while 66.7% (24/36) of the previously published patients had developmental delay." (PMID 35359574, 2022).
tauopathy (3 papers, 2018 to 2023). Neurodegenerative disorders involving deposition of abnormal tau protein isoforms (tau proteins) in neurons and glial cells in the brain. "Collectively, these findings suggest that tauopathies could lead to lower expression of the inhibitory channel proteins, including GABRG2, possibly through loss of these neurons in affected brain areas." (PMID 32400971, 2020). "To begin to address this question, we examined temporal expression of Gabbr1, Gabrb2, Gabrb3, and Gabrg2 in a mouse model of tauopathy that overexpresses human MAPT p.P301L37." (PMID 30546007, 2018). "Similarly, GABRG2 expression was found to be significantly low in symptomatic mouse models of tauopathy." (PMID 36970514, 2023). "Interestingly, we found that GABA receptor genes, including GABRB2 and GABRG2, are significantly lower in symptomatic mouse models of tauopathy, as well as in brains with progressive supranuclear palsy." (PMID 30546007, 2018). "The expression of GABA receptor genes, including GABRB2 and GABRG2, were consistently reduced in iPSC-derived neurons and brains from MAPT p.R406W carriers, PSP brains, and mouse models of tauopathy." (PMID 30546007, 2018).
alcohol dependence (2 papers, 2012 to 2020). Physical and psychological dependence on alcohol. "The top candidate genes that we identified include genes which have previously been associated with alcoholism, such as Gabrg2, Gabrb3 and Gria3, but also genes that have not been associated with alcoholism before." (PMID 22629472, 2012).
alcohol use disorder (2 papers, 2016 to 2024). "Pafah1b1 has been shown to be co-expressed with GABA type-A receptor subunits (specifically Gabra1, Gabrb2, and Gabrg2), a family of neurochemical receptors associated with alcohol-use disorder." (PMID 26834590, 2016). "Not only has GABRG2 been linked to both alcohol use disorder and OUD, but we previously demonstrated a microglia-specific upregulation of GABRG2 in OUD using single nuclei transcriptomics in human OUD." (PMID 39399686, 2024).
autism (2 papers, 2017 to 2024). Persistent deficits in social interaction and communication and interaction as well as a markedly restricted repertoire of activity and interest as well as repetitive patterns of behavior. "However, TXGNN Explainer indicated that zolpidem’s action on GABRG2 might reduce autism susceptibility and improve pre-frontal cortex function." (PMID 39148855, 2024).
breast carcinoma (2 papers, 2022 to 2025). "GABRG2 variants may be resistant to valproic acid, and our study found that GABRG2 is highly correlated with square_ngtdm_Busyness characteristics, and GABRG2 may also be a possible therapeutic target for breast cancer." (PMID 36553681, 2022).
colon cancer (2 papers, 2024 to 2025). "In the colon tumors, MEBOCOST analysis revealed that GABA mediated the mCCC between colon cancer and NK cells through two sensors, namely, SLC6A6 and GABRG2." (PMID 40568942, 2025). "Gene expression of GABRB3, GABRG2, and GAD1 positively correlated with genes involved in the synthesis of PGE2 (PTGS2 and PTGES) as well as IL‐6 in human colon cancer." (PMID 38886975, 2024).
COVID-19 (2 papers, 2022 to 2025). A disease caused by infection with severe acute respiratory syndrome coronavirus 2. "Most striking is GABRG2, which showed only marginal expression in all PBMCs, but a conspicuous, 24-fold increase in γδ T cells derived from the COVID-19 samples." (PMID 35773312, 2022). "Like GABRG2, expression in γδ T cells increases approximately threefold in the COVID-19 samples." (PMID 35773312, 2022).
Cushing syndrome (2 papers, 2022 to 2024). Cushing's syndrome (CS) encompasses a group of hormonal disorders caused by prolonged and high exposure levels to glucocorticoids that can be of either endogenous (adrenal cortex production) or exogenous (iatrogenic) origin. "In a mouse model of iatrogenic Cushing’s syndrome, knockout of the Dbi gene, mutation of Gabrg2, antibody-mediated neutralization of ACBP/DBI or transcriptional downregulation of ACBI/DBI by thyroid hormone all prevent the metabolic consequences of chronic glucocorticoid administration." (PMID 39578649, 2024).
insomnia (2 papers, 2021 to 2024). A sleep disorder characterized by difficulty in falling asleep and/or remaining asleep. "Amongst the various subunits of the GABAA receptor family implicated in insomnia mediation are frequently reported ones such as GABRA1 and GABRG2." (PMID 38463787, 2024). "Of the GABAA receptor subunits, GABRA1 and GABRG2 have been frequently reported to mediate insomnia." (PMID 35002696, 2021). "GABAARα1 (GABRA1) and GABAARγ2 (GABRG2) are two significant subunits of GABA receptors, and are known to play an important role in the first line treatment of insomnia." (PMID 35002696, 2021).
temporal lobe epilepsy (2 papers, 2022 to 2024). A localization-related (focal) form of epilepsy characterized by recurrent seizures that arise from foci within the temporal lobe, most commonly from its mesial aspect. "Limited to patients with temporal lobe epilepsy, we detected a significant correlation between the exponent and the cortical expression of GABRA1, GRIN2A, GABRD, GABRG2, KCNA2 and PDYN genes." (PMID 39056027, 2024).
absence seizures (1 paper, 2024). "Although genes encoding GABA receptor subunits, including GABRA1, GABRB3, and GABRG2, have been associated with absence epilepsy, they have also been implicated in other forms of epilepsy, indicating that the GABA receptor dysfunction is not specifically linked to absence seizures." (PMID 39337309, 2024).
channelopathy (1 paper, 2022). Channelopathies are a group of diseases caused by the dysfunction of ion channel subunits or their interacting proteins. "The underlying channelopathy pathway accounted for 46.7% (7/15) of the monogenic variants, including ion channel genes (SCN1A, KCTD7, KCNC1, CACNA1A, KCNMA1) and ligand-gated ion channel genes (GABRA1, GABRG2)." (PMID 36034301, 2022).
colon adenocarcinoma (1 paper, 2022). "Ling Yan and colleagues showed that overexpression of GABRA2, GABRA3, GABRB3, GABRG2, GABRG3, GABRD, and GABRE might be diagnostic for colon adenocarcinoma." (PMID 35565356, 2022).
convulsion (1 paper, 2011). A rapid and repeated body muscle contract that results in an uncontrolled shaking of the body. "Only the FEB2, FEB5 and FEB8 loci have been reported for pure febrile convulsions (although the gene for FEB8, GABRG2, has also been found mutated in GEFS+)." (PMID 21858011, 2011).
delirium (1 paper, 2023). A disorder characterized by confusion; inattentiveness; disorientation; illusions; hallucinations; agitation; and in some instances autonomic nervous system overactivity. "Fluctuations in core clinical features of DLB are typically delirium-like, occurring as spontaneous alterations in cognition, attention, and arousal, which is different from PDD; similarly, in our study, GABRA1 and GABRG2 genes were downregulated in DLB." (PMID 36970514, 2023).
dyslipidaemia (1 paper, 2024). "Gabrg2 F77I mutation also prevented CORT-induced signs of dyslipidaemia, hyperinsulinaemia and insulin resistance." (PMID 39578649, 2024).
esophageal carcinoma (1 paper, 2024). A primary or metastatic malignant neoplasm involving the esophagus. "As the gene with the strongest degree of interaction in PPI, the biological role of GABRG2 overexpression in hypopharyngeal carcinoma with esophageal carcinoma deserves further study through in vitro and in vivo research." (PMID 38877096, 2024). "GABRG2, CNTNAP2, and SCN4B in the hub genes have high diagnostic value in determining whether hypopharyngeal carcinoma patients have combined esophageal carcinoma (AUC: 0.944, 0.944, 0.972)." (PMID 38877096, 2024).
head and neck squamous cell carcinoma (1 paper, 2024). A squamous cell carcinoma that arises from any of the following anatomic sites: lip and oral cavity, nasal cavity, paranasal sinuses, pharynx, larynx, and salivary glands. "There is relatively little research on GABRG2 in head and neck squamous cell carcinoma." (PMID 38877096, 2024).
liver cancer (1 paper, 2025). An epithelial or non-epithelial malignant neoplasm that arises from the liver. "It appears probable that ACBP/DBI neutralization affects both cell-intrinsic and -extrinsic facets of liver cancer, in line with the fact that both hepatocytes and immune cells express GABRG2." (PMID 40628264, 2025).
nicotine addiction (1 paper, 2023). "The GABRA2 and GABRG2 genes were related to three signaling pathways, including hsa05033, nicotine addiction; hsa04727, GABAergic synapse; and hsa05032, morphine addiction." (PMID 37324729, 2023).
Obesity (1 paper, 2022). Accumulation of substantial excess body fat. "Loss of Gabrg2 in the PVN leads to obesity and loss of diurnal rhythm of energy expenditure and food intake." (PMID 35215509, 2022). "In the PVN of the hypothalamus, Gabrg2 protein has been implicated in diurnal rhythmicity in metabolism and diet-induced obesity through upstream regulation by the circadian gene Bmal1." (PMID 35215509, 2022).
status epilepticus (1 paper, 2023). Status epilepticus is defined as a continuous seizure lasting more than 30 min, or two or more seizures without full recovery of consciousness between any of them. "Particularly, induced SWOs in vivo can increase SWD duration up to status epilepticus in some het Gabrg2+/Q390X KI mice." (PMID 36632186, 2023).
tumour (3 papers, 2015 to 2025). "First, we expressed a construct encoding the GABAA subunit GABRG2 tagged with GFP in patient-derived DMG tumour cells and subsequently xenografted these GABAAR subunit-tagged tumour cells to the mouse hippocampus, a region to which DMG frequently spreads, allowing engraftment for 8 weeks." (PMID 39972132, 2025). "Of note, ACBP/DBI inhibition by Dbi knockout, Gabrg2 mutation, or KLH-ACBP/DBI vaccination resulted in reduced proliferation, both in tumor lesions (if detectable) and in the non-malignant hepatic parenchyma, irrespective of the precise oncogenic stimulus (CCl4 or DEN)." (PMID 40628264, 2025).
neuro(developmental) disorders (2 papers, 2022).
psychiatric disorder (2 papers, 2016 to 2025). A disorder characterized by behavioral and/or psychological abnormalities, often accompanied by physical symptoms. "Instead, other groups have previously demonstrated an involvement of Slc22a2 or Htr4 in the efficacy of antidepressant medication, whereas Gabrg2 holds high relevance seen the involvement of GABAergic transmission in several psychiatric disorders." (PMID 27824361, 2016).
metabolic disease (1 paper, 2024). A congenital disorder (due to inherited enzyme abnormality) or acquired (due to failure of a metabolically important organ) disorder resulting from an abnormal metabolic process. "The appetite stimulatory and metabolic disease-inducing effects of ACBP/DBI are lost in mice bearing a point mutation (F77I) in Gabrg2 that abolishes the receptor-ligand interaction." (PMID 38582872, 2024).
neurological disorders (1 paper, 2019). "Interestingly, the GABRG2 variant occurred at low rate percentage in blood and buccal swabs, reinforcing the relevance of mosaicism in neurological disorders." (PMID 31344879, 2019).
GABRG2 also shares sentences with these, for which no sentence is quoted: developmental and epileptic encephalopathy (5 papers); childhood absence epilepsy (4); cognitive deficits (4); behavioral disorders (3); cancer (3); Intellectual disability (3); Rett syndrome (3); Seizure (3); Alzheimer disease (2); Doose syndrome (2); Myoclonus (2); psychosis (2); Tremor (2); alcoholism (1); Angelman syndrome (1); Ataxia (1); autism spectrum disorder (1); bipolar disorder (1); brain malformations (1); cognitive decline (1); dementia (1); Dyskinesia (1); dyspraxia (1); Dystonia (1); encephalitis (1); frontotemporal dementia (1); genetic disorders (1); genetic generalized epilepsy (1); glioblastoma (1); Hirschsprung disease (1).
A further 23 diseases each share a sentence with GABRG2 in 1 paper.